SNORD116-6 (small nucleolar RNA, C/D box 116-6)
Synonyms: HBII-85-6
Gene: Small nucleolar RNA gene on chromosome 15 (25,065,026 to 25,065,121, forward strand). Ensembl gene ENSG00000207442.
Gene Ontology:
Biological process: RNA processing
Cellular component: nucleolus
Homologues: Orthologues: macaque SNORD116 (96% identical), rabbit SNORD116 (88% identical), rabbit SNORD116 (86% identical), rabbit SNORD116 (85% identical), rabbit SNORD116 (84% identical), rabbit SNORD116 (83% identical), rabbit SNORD116 (81% identical), rabbit SNORD116 (80% identical), rabbit SNORD116 (78% identical), rabbit SNORD116 (76% identical). Paralogues in human: SNORD116-2 (98% identical), SNORD116-4 (96% identical), SNORD116-8 (96% identical), SNORD116-1 (94% identical), SNORD116-3 (94% identical), SNORD116-9 (94% identical), SNORD116-5 (93% identical), SNORD116-7 (93% identical), SNORD116-14 (86% identical), SNORD116-17 (85% identical), SNORD116-19 (85% identical), SNORD116-21 (85% identical), and 20 more.